DHX9 (DExH-box helicase 9)
Diseases named in the same sentence as DHX9 in open-access papers (continued):
Sharing a sentence is not in itself a finding about the gene and the disease.
non-small cell lung carcinoma (6 papers, 2007 to 2024). A group of at least three distinct histological types of lung cancer, including non-small cell squamous cell carcinoma, adenocarcinoma, and large cell carcinoma. "Therefore, long noncoding RNA SH3PXD2A-AS1 interacts with Dhx9 to facilitate proliferation and cell cycle progression in non-small-cell lung carcinoma." (PMID 39220589, 2024). "Upregulated STAT3 has been shown to promote EMT in non-small-cell lung cancer, therefore, it is speculated that DHX9 mediates EMT via STAT3 regulation in lung adenocarcinoma." (PMID 33437516, 2020). "It is speculated that enoxacin enhances RNA interference dependent on DHX9 expression in non-small-cell lung cancer cells, inhibiting their proliferation." (PMID 33437516, 2020). "Another study revealed that HIF1A-As2 epigenetically activates MYC by attracting DHX9 to the MYC promoter, thereby promoting the transcription of MYC and its target genes in KRAS-driven non-small cell lung cancer." (PMID 39668816, 2024). "DHX9 promotes migration of lung adenocarcinoma cells, whereas DHX36 knockdown increases migration and proliferation and reduces chemotherapeutic responses in non-small-cell lung carcinoma (NSCLC)." (PMID 36012592, 2022).
osteosarcoma (6 papers, 2013 to 2023). A usually aggressive malignant bone-forming mesenchymal neoplasm, predominantly affecting adolescents and young adults. "Taken together, MCM2 and MCM3 were correlated with DHX9 in tumor samples and were associated with poor prognosis in osteosarcoma patients." (PMID 28460433, 2017). "Taken together, MCM2 and MCM3 promote osteosarcoma progression via associations with DHX9 and thus are potential therapeutic targets for patients with osteosarcoma." (PMID 28460433, 2017). "Notably, MCM2 and MCM3 expression levels were positively correlated with the DHX9 expression level in tumor samples and were associated with a poor prognosis in patients with osteosarcoma." (PMID 28460433, 2017). "Thus, MCM2 and MCM3 are associated with DHX9 in osteosarcoma cells." (PMID 28460433, 2017). "A Spearman correlation analysis revealed a significant correlation between the expression levels of MCM2 and DHX9 (R = 0.195, P = 0.027), as well as between the levels of MCM3 and DHX9 (R = 0.248, P = 0.005) in osteosarcoma tissues." (PMID 28460433, 2017). "A positive correlation between MCM2 or MCM3 and DHX9 expression was detected in osteosarcoma tissues." (PMID 28460433, 2017). "Collectively, these results reveal that knockdown of MCM2 or MCM3 inhibits osteosarcoma cell proliferation via DHX9 and DHX9 plays an oncogenic role in osteosarcoma." (PMID 28460433, 2017). "In co-immunoprecipitation and co-localization experiments, MCM2 and MCM3 were found to interact with DExH-box helicase 9 (DHX9) in osteosarcoma cells." (PMID 28460433, 2017). "Since MMC2 and MCM3 interact with DHX9 in osteosarcoma cells, it is plausible that they function via DHX9, and DHX9 plays an important role in osteosarcoma cell proliferation." (PMID 28460433, 2017). "This study, for the first time, demonstrates the interactions of MCM2/MCM3 with DHX9 in osteosarcoma cells." (PMID 28460433, 2017). "Second, the c-MYC sequence-containing plasmid (pMEXr) increased the frequencies of mutations in human osteosarcoma U2OS cells, and transient DHX9 deficiency exacerbated these mutations, which comprised of deletions for the most part." (PMID 24049074, 2013). "Overexpression of DHX9 has previously been identified in osteosarcoma cells exhibiting high metastatic ability, and these studies highlight the ability of DHX9 to both promote oncogenic and inhibit tumor suppressive circRNAs to promote invasion, migration and metastasis in CRC and HCC." (PMID 33437516, 2020). "MCM2 and MCM3 were found to interact and co-localize with DHX9 in osteosarcoma." (PMID 28460433, 2017). "Then, DHX9-specific siRNA was used to knockdown DHX9 in osteosarcoma cells." (PMID 28460433, 2017). "Further analyses showed that the inhibition of DHX9 hindered osteosarcoma cell proliferation." (PMID 28460433, 2017). "More importantly, this report provides, for the first time, experimental evidence for interactions of MCM2 and MCM3 with DHX9 in osteosarcoma cells and the importance of these interactions, clarifying the molecular mechanisms of MCM2 or MCM3-mediated tumorigenesis." (PMID 28460433, 2017). "Additionally, our results showed that knockdown of DHX9 inhibited osteosarcoma cell proliferation." (PMID 28460433, 2017). "Finally, we detected the expression of DHX9 in osteosarcoma tissues." (PMID 28460433, 2017). "In addition, positive correlations between both MCM2 and MCM3 and DHX9 were found in osteosarcoma." (PMID 28460433, 2017). "In addition, the depletion of DHX9 hindered osteosarcoma cell proliferation." (PMID 28460433, 2017). "A rescue study showed that the decreased growth of osteosarcoma cells by MCM2 or MCM3 knockdown was reversed by DHX9 overexpression, indicating that MCM2 and MCM3 activity was DHX9-dependent." (PMID 28460433, 2017). "Overexpression of DHX9 rescued the MCM2 and MCM3 knockdown-induced osteosarcoma growth inhibition by regulating numerous biological processes." (PMID 28460433, 2017).
osteosarcoma (continued). "The overexpression of DHX9 rescued the MCM2 and MCM3 knockdown-induced osteosarcoma growth inhibition, showing that the control of cell proliferation by MCM2 and MCM3 was largely dependent on DHX9." (PMID 28460433, 2017). "However, the role of DHX9 in osteosarcoma and whether MCM2 and MCM3 function via DHX9 are largely unknown." (PMID 28460433, 2017).
sarcoma (6 papers, 2016 to 2023). A usually aggressive malignant neoplasm of the soft tissue or bone. "However, as previously reported, in Ewing Sarcomas cell lines (SK-N-MC cells), irradiation induced a new isoform of the RNA helicase DHX9, which was targeted to nonsense-mediated decay (NMD) and caused downregulation of DHX9 expression." (PMID 35814441, 2022).
autoimmune disease (5 papers, 2009 to 2025). A disorder resulting from loss of function or tissue destruction of an organ or multiple organs, arising from humoral or cellular immune responses of the individual to their own tissue constituents. "Consistent with regarding defects T cell development and poor TRA expression in mTECs in Dhx9 cKO mice, Dhx9 deficiency in TECs resulted in spontaneous autoimmune diseases, characterized by obvious organ lymphocyte infiltration and the existence of antinuclear antibodies." (PMID 35720303, 2022). "Importantly, incompetent mTECs in Dhx9 cKO mice impaired T cell differentiation, inhibited the central immune tolerance establishment, and caused autoimmune disorders in mice." (PMID 35720303, 2022). "As an important indicator of autoimmune disease, lymphocytic infiltration in multiple organs from 8-month-old WT, and Dhx9 cKO mice were measured by hematoxylin and eosin (H&E) straining." (PMID 35720303, 2022). "In a summary, our study showed that Dhx9 was an important regulation for the development and maturation of mTECs and was indispensable for the central immune tolerance establishment and the prevention of autoimmune diseases." (PMID 35720303, 2022). "Our results showed that Dhx9 deletion in TECs resulted in severe thymus atrophy with the accelerated mTEC maturation, central immune tolerance disruption, and spontaneous development of autoimmune diseases." (PMID 35720303, 2022). "Importantly, Dhx9 cKO mice displayed an impaired thymopoiesis, poor thymic T cell output, and they suffered from spontaneous autoimmune disorders." (PMID 35720303, 2022).
ovarian carcinoma (5 papers, 2022 to 2025). A malignant neoplasm originating from the surface ovarian epithelium. "And their down-regulation in the plasma or tissue levels of ovarian cancer patients was possibly caused by the suppression of the oncogenic RNA binding proteins, such as in DHX9 and ADAR1." (PMID 35550610, 2022).
renal carcinoma (5 papers, 2021 to 2025). A carcinoma arising from the epithelium of the renal parenchyma or the renal pelvis. "This regulation is likely direct, as AR is specifically recruited to the DHX9 promoter in LNCaP cells, as previously reported in renal carcinoma cells, while AR inhibition under androgen deprivation or enzalutamide treatment caused repression of DHX9 expression." (PMID 35590370, 2022). "In liver, lung, breast and renal cancer cells, the knockdown or depletion of DHX9 significantly affected the proliferation, metastasis and EMT process of cancer cells." (PMID 37214432, 2023). "Previous studies indicated that the knockdown of DHX9 enhanced the proliferation and migration of thyroid cancer and renal cancer cells." (PMID 37214432, 2023). "Furthermore, in vivo and in vitro experiments revealed that DHX9 could affect the proliferation, metastasis of liver, lung, breast and renal cancer cells via regulating EMT." (PMID 37214432, 2023).
small cell lung carcinoma (5 papers, 2007 to 2025). Small cell lung cancer (SCLC) is a highly aggressive malignant neoplasm, accounting for 10-15% of lung cancer cases, characterized byrapid growth, and early metastasis. "For example, the DHX9 helicase identified as a repressor for both dsRNA and dsDNA induced by DNA damage was aberrantly overexpressed in small cell lung cancer." (PMID 40492347, 2025). "Targeting DHX9 triggers tumor-intrinsic interferon response and replication stress in small-cell lung cancer." (PMID 39941810, 2025). "The expression of DHX9 was much higher in the small-cell lung cancer cell line H446 than in the non-small-cell lung carcinoma cell lines A549 and PC9." (PMID 35804828, 2022).
systemic lupus erythematosus (5 papers, 2010 to 2024). An autoimmune multi-organ disease typically associated with vasculopathy and autoantibody production. "DExH-box helicase 9 (DHX9), a member of the DExD/H-box RNA helicase superfamily II, is an autoantigen that induces serum inflammation in patients with systemic lupus erythematosus." (PMID 39457485, 2024). "DHX9 is identified as an autoantigen in the sera of systemic lupus erythematosus patients to trigger inflammation and complications such as skin rashes, and atherosclerosis." (PMID 37326773, 2023). "DExH-Box helicase 9 (DHX9), as a member of DExD/H-box RNA helicase superfamily II, is identified as an autoantigen in the sera of systemic lupus erythematosus patients to trigger inflammation." (PMID 37326773, 2023).
lung adenocarcinoma (4 papers, 2020 to 2024). A carcinoma that arises from the lung and is characterized by the presence of malignant glandular epithelial cells. "As with most functions of DHX9, there is a converse role for the helicase in lung adenocarcinoma where DHX9 functions as a tumor suppressor and inhibits EMT." (PMID 33437516, 2020). "Additionally, the downregulation of DHX9 can suppress the progression of certain tumors, such as lung adenocarcinoma." (PMID 36377508, 2023).
breast tumor (3 papers, 2017 to 2023). "We determined that LINC01016 promoted TNBC cell proliferation and invasion by binding to and stabilizing DHX9 protein through competitive inhibition of the E3 ubiquitin ligase RFFL, thus activated DHX9-mediated PI3K/AKT signaling to accelerate breast tumor progression." (PMID 37550275, 2023). "In primary human breast tumors, the most common ITGB1 isoform 1 A was positively correlated to Suppressor-SFs such as DDX3X and DHX9 while being negatively correlated to Enhancer-SFs such as CCDC12 and FAM50A." (PMID 30940821, 2019). "Together, this study demonstrates two previously uncharacterized factors AK023948 and DHX9 as important players in the AKT pathway, and that their upregulation may contribute to breast tumour progression." (PMID 28176758, 2017).
leukemia (3 papers, 2023). A malignant (clonal) hematologic disorder, involving hematopoietic stem cells and characterized by the presence of primitive or atypical myeloid or lymphoid cells in the bone marrow and the blood. "DHX9 is essential for the maintenance of malignant proliferation of leukemia cells, and DHX9 suppression increases cell apoptosis and causes hypersensitivity to chemotherapeutic agents." (PMID 37305700, 2023). "Taken together, the suppression of DHX9 increases cell apoptosis and caused leukemia cells to be more sensitive to apoptosis induced by chemotherapeutic agents." (PMID 37305700, 2023). "Consistent with their findings, we investigated p-Chk1 expression was diminished in DHX9-depleted MDS/leukemia cells, suggesting that DHX9 maintain ATR-Chk1 activity in response to DNA damage." (PMID 37305700, 2023). "In vitro experiments, DHX9 was found to be essential for the proliferation of leukemia cells, and the knockdown of DHX9 reduced cell growth, induced cell apoptosis and sensitivity to chemotherapeutic drugs." (PMID 37305700, 2023). "Previous studies have demonstrated that DHX9 is recruited to promyelocytic leukemia nuclear bodies (PML-NBs) in response to IFN-α stimulation and could be involved in the transcriptional regulation of some ISGs attached to PML-NBs." (PMID 36735791, 2023). "To investigate whether MDS cells overcome apoptosis through DHX9, annexin V-FITC/PI assay was performed and then we observed that knockdown of DHX9 increased the apoptosis in leukemia cell lines." (PMID 37305700, 2023). "We determined the expression of DHX9 in MDS patients and performed a series of functional experiments to investigate the effects of DHX9 on biological characteristics of MDS/leukemia cells." (PMID 37305700, 2023). "Although we revealed the connection among DHX9, R-loop, PI3K-AKT, and ATR-Chk1 pathway in MDS/leukemia cell lines, the reciprocal relationship among them needs to be further investigated." (PMID 37305700, 2023).
liver cancer (3 papers, 2021 to 2023). An epithelial or non-epithelial malignant neoplasm that arises from the liver. "In liver cancer patients, a elevated expression of DHX9 was found to be significantly associated with an unfavorable OS, RFS, PFS, and disease-specific survival (DSS)." (PMID 37214432, 2023). "Because DHX9 had the highest expression level and amplification mutation frequencies in liver tumors, we explored its effect on DDR and radiosensitivity in liver cancer cell lines through colony formation, alkaline comet assay, immunofluorescence, and western blotting." (PMID 35814441, 2022). "Additionally, DHX9 interacts with NONO and SFPQ to form a DHX9-NONO-SFPQ complex, a key regulator in liver cancer." (PMID 34512155, 2021).
renal cell carcinoma (3 papers, 2021 to 2023). "Notably, a recent study reported that AR binds the DHX9 promoter in renal cell carcinoma and that this event is associated with osteolytic formation and bone metastasis, suggesting the possibility of a crosstalk between AR and DHX9." (PMID 35590370, 2022).
esophageal cancer (2 papers, 2023 to 2025). A primary or metastatic malignant neoplasm involving the esophagus. "In esophageal cancer, RNA–protein interaction assays have shown that CARINH interacts with ILF3 (Interleukin Enhancer Binding Factor 3) and DHX9 (DExH-Box Helicase 9) to control the expression of the CARINH and IRF1 locus via a feedforward mechanism." (PMID 39773901, 2025).
melanoma (2 papers, 2020 to 2023). A malignant, usually aggressive tumor composed of atypical, neoplastic melanocytes. "Other tested DNA sensors (Cgas, Sting, Ddx41, Dhx9, Dhx36, Lrrfip1, Mre11, and additionally Aim2, which is absent in melanoma cells) were expressed in macrophages but were not significantly upregulated after irradiation." (PMID 33202881, 2020).
myelodysplastic syndrome (2 papers, 2023 to 2025). A clonal hematopoietic disorder characterized by dysplasia and ineffective hematopoiesis in one or more of the hematopoietic cell lines. "Knockdown of DHX9 in myelodysplastic syndromes inactivates PI3K-AKT signaling." (PMID 39941810, 2025).
pancreatic cancer (2 papers, 2017 to 2021). "This is particularly significant because in human cancer cells that are nonpermissive for MYXV, for example, PANC-1 human pancreatic cancer cells, DHX9 knockdown alone increased MYXV replication by more than 2 orders of magnitude." (PMID 33952639, 2021). "We further extended these observations in nonpermissive human PANC-1 pancreatic cancer cells, where MYXV infection alone makes few if any progeny virions, and tested whether DHX9 knockdown enhanced MYXV progeny virion formation." (PMID 33952639, 2021).
Papillary Thyroid Cancer (2 papers, 2021 to 2025). "Conversely, in papillary thyroid cancer, DHX9 exhibits an opposing effect, dampening cell proliferation and migration." (PMID 39941810, 2025). "Conversely, in papillary thyroid carcinoma, DHX9 silencing activates the AKT pathway." (PMID 39941810, 2025).
prostate adenocarcinoma (2 papers, 2023 to 2025). "It was determined that 21 proteins (DHX9, EIF5, HPRT1, INPP5B, MCM6, PPP6C, SYF2, etc.)whose expression was increased in PC3‐R cells based on label‐free nLC‐MS/MS analysis were consistent with both TCGA prostate adenocarcinoma N0 and N1 nodal metastasis status and correlation data." (PMID 39799471, 2025).
Rotavirus infection (2 papers, 2022 to 2024). Infection with any of the rotaviruses. "DHX9 promotes antiviral signaling by sensing dsRNA and activating the NLRP9b inflammasome in response to rotavirus infection in intestinal epithelial cells, although whether DHX9 is sensing a specific secondary structure in the dsRNA that is acting as a PAMP remains to be seen." (PMID 35626643, 2022). "Furthermore, DHX9 pairs with Nlrp9b to sense short dsRNA, forming inflammasome complexes that promote the maturation of interleukin-18 and GSDMD-induced pyroptosis, thus providing resistance against rotavirus infection in IECs18." (PMID 38594251, 2024).